BRAF (B-Raf proto-oncogene, serine/threonine kinase)
Diseases named in the same sentence as BRAF in open-access papers (continued):
Sharing a sentence is not in itself a finding about the gene and the disease.
melanoma (continued). "It is recommended for patients with advanced melanoma and disease progression under ipilimumab and BRAF inhibitors, in the case of the patients with BRAF mutation." (PMID 30417020, 2018). "We next showed that exposure of BRAF-mutated melanoma cells to MAPK pathway inhibitors enhanced stemness features by upregulating the expression of YAP/TAZ and downstream genes but surprisingly not SCD1." (PMID 30558661, 2018). "Approximately 50% of melanomas in Caucasian patients harbor BRAF mutations, resulting in constitutive BRAF kinase activity." (PMID 29724167, 2018). "Another approach approved by the FDA for the treatment of metastatic melanomas with BRAF mutations is the combination of cobimetinib with vemurafenib." (PMID 29455659, 2018). "Fortunately, it has been commonly recognized that trametinib is indispensable for treatment for BRAF mutated melanoma." (PMID 29731968, 2018). "In a similar study, sensitivity of BRAF to 17-AAG also extended selectively to melanoma cell lines with BRAFV600E mutations." (PMID 29481571, 2018). "The introduction of specific kinase inhibitors for melanoma patients carrying this BRAF mutation has revolutionised melanoma care." (PMID 30290811, 2018). "This study is the first to demonstrate the potential of AgGom and HiGom in treating human melanoma containing BRAF mutations." (PMID 30068931, 2018). "An adaptive response that is lost in melanoma patients harboring mutations in USP28 resulting in BRAF stabilization, hyperactivation of the MAPK signaling, and resistance to therapies targeting this pathway." (PMID 29880484, 2018). "Mutations in BRAF are found in up to 66% of melanoma patients, 18% of colorectal carcinomas and in 66% of papillary thyroid carcinoma cases and are associated with poor prognosis." (PMID 29455659, 2018). "We first tested our models with SOC therapy to address the issue that despite the commonality of the driver BRAF mutation in melanoma tumors, tumor heterogeneity contributes to different treatment responses." (PMID 29541385, 2018). "Correspondingly, it has been shown that BRAF mutations are exceedingly rare in predominantly oral canine malignant melanoma and, to date, few alterations in other MAPK members have been discovered." (PMID 30188888, 2018). "Overall, our data support the role of SCD1 as a promising therapeutic target in combination with MAPKi in BRAF mutated melanoma and suggest a possible function as diagnostic and prognostic marker." (PMID 30558661, 2018). "Approximately 60% of melanomas were caused by mutations in the BRAF gene and resulted in an alteration of BRAF protein expression that leads to the activation of downstream signaling in the MAP kinase pathway." (PMID 30544544, 2018). "Somatic mutations in the BRAF gene were initially discovered in melanomas and in a wide range of other cancers including colorectal and ovarian tumours as early as 2002." (PMID 29098416, 2018). "Despite this high genetic heterogeneity, 40–60% of melanoma patients carry mutations in the Ser/Thr-kinase BRAF (most often V600E), which renders the BRAF kinase and the downstream MAPK signalling pathway constitutively active." (PMID 30290811, 2018). "Melanoma patients with the BRAF-V600E mutation have been treated with the drug vemurafenib (VEM) which targets this mutation." (PMID 29416666, 2018). "For example, smart searches like ‘melanoma cell lines with BRAF mutation’ or ‘lung cancer cell lines with high EGFR expression’ can be easily achieved by Boolean logic queries." (PMID 29726944, 2018). "Currently, combination therapy with dual inhibition of BRAF and MEK is considered standard treatment for BRAF mutated melanoma." (PMID 29946532, 2018). "Recent studies show that advanced melanoma and colorectal cancer patients with non-V600 BRAF mutation have longer overall survival compared those with both V600E BRAF mutant and wild-type BRAF." (PMID 29739364, 2018).
melanoma (continued). "In the same year pembrolizumab was also approved by the FDA for treatment of advanced melanoma in patients previously treated with ipilimumab or BRAF inhibitors in BRAF V600 mutation positive patients." (PMID 29371600, 2018). "Two phase III studies on melanoma patients were conducted with nivolumab compared with dacarbazine, either on patients with wild type or mutated BRAF, the latter unresponsive to ipilimumab." (PMID 29371600, 2018). "The most common melanoma genetic mutation, BRAF, is a near-perfect biomarker predictive of sensitivity to BRAF targeted therapies in both advanced and high-risk resected melanoma." (PMID 30010756, 2018). "MEK inhibitors are some of the most successful molecular-targeting drugs in recent years, as symbolized by the approval of trametinib against BRAF-mutated melanoma." (PMID 29731968, 2018). "Mutation of the BRAF gene can be found in approximately 50% of advanced (stage IIIC) or metastatic (stage IV) melanomas." (PMID 30181812, 2018). "BRAF-mutated melanoma 3D cultures enriched for CSCs overexpressed SCD1 and were more resistant than 2D differentiated cultures to BRAF and MEK inhibitors." (PMID 30558661, 2018). "On another note, almost half of melanoma patients carry a mutation (V600E) in the BRAF oncogene which results in an amino acid substitution, at amino acid 600, from a valine (V) to a glutamic acid (E)." (PMID 30013176, 2018). "Randomized phase III trials demonstrated that the BRAF inhibitors namely vemurafenib and dabrafenib achieve an efficient targeting of BRAF-mutated melanoma." (PMID 30558661, 2018). "Fourty percent of all melanomas harbor a mutation in the signaling adaptor BRAF (V600E) that results in ERK hyperactivity as an oncogenic driver." (PMID 29983861, 2018). "Independently, MEKi also improve overall survival in patients with melanoma harbouring BRAF V600E mutations compared with chemotherapy." (PMID 30072489, 2018). "For example, the BRAF V600E mutation in melanoma patients can be used to predict response to BRAF inhibitors such as vemurafenib." (PMID 29368597, 2018). "On the other hand, MEK, and BRAF inhibitors revert TADC suppression enforced by mutated melanoma cells in vitro." (PMID 30233579, 2018). "Metastatic melanomas are subdivided by their mutation profile into four subtypes BRAF driven (about 52%), NRAS driven (28%), Neurofibromin 1 (NF1) mutated (14%) and in “triple wild type”." (PMID 30360441, 2018). "Binimetinib is an allosteric selective, ATP-non-competitive inhibitor of MEK1/2 that demonstrated anti-tumoral activity by abrogating the growth of NRAS- and V600E BRAF-mutated melanomas in preclinical studies using in vitro and in vivo models." (PMID 29455659, 2018). "BRAF-mutated melanoma tends to exhibit distinctive clinical features and is characterized by more aggressive biological behavior than BRAF wild-type (WT) melanoma." (PMID 29148538, 2018). "BRAF inhibitor PLX4032 (vemurafenib) is very effective in treating malignant melanoma patients with BRAFV600E mutation." (PMID 30100999, 2018). "BRAF mutations in melanoma, colorectal, NSCLC and cholangiocarcinoma cohorts, with treatment using sorafenib tosylate or regorafenib." (PMID 29507702, 2018). "Given the computational burden, we opted for a biologically-guided search (i.e., searching for BRAF-related genetic associations in melanoma) that ultimately led to compelling associations between genes and drug responses." (PMID 29435161, 2018). "In 2002, for the first time, Davies and collaborators reported the presence of the—now well-known—somatic point mutation V600E in the BRAF gene in human malignant melanomas." (PMID 29534457, 2018). "In this study, we examined POM for alterations in candidate melanoma driver genes (BRAF, NRAS, KRAS, GNA11, GNAQ) and genes implicated in UM prognosis (EIF1AX, SF3B1, BAP1)." (PMID 30558566, 2018).
melanoma (continued). "Lung adenocarcinoma, melanoma and colorectal cancer with BRAF mutation showed 50–86, 34 and 23% non-V600 BRAF mutation frequency, respectively." (PMID 29739364, 2018). "In small numbers of patients, specific BRAF inhibitors (PLX 4032 and RAF 265) induced tumour regression in up to 70% of patients with BRAF V 600 E mutated metastatic melanomas." (PMID 29492238, 2018). "The findings of this study suggest that melanoma patients with BRAF or NRAS mutant tumours have an increased risk compared to patients with BRAF/NRAS wild-type tumours of developing disease recurrence following a tumour-negative SLNB." (PMID 29755118, 2018). "For BRAF mutation-positive patients with melanoma, BRAF inhibitors such as vemurafenib or dabrafenib were regarded as the standard therapy, but in a short time the combination of BRAF inhibitor and MEK inhibitor became the standard therapy." (PMID 29942670, 2018). "Adjuvant dabrafenib and trametinib in the treatment of BRAF-mutated melanoma provides intermediate value." (PMID 30116683, 2018). "Clinical trials demonstrated its therapeutic value for melanomas carrying the activating BRAF mutation." (PMID 30191142, 2018). "Approximately half of all melanoma patients harbour activating mutations in the serine/threonine kinase BRAF." (PMID 30237393, 2018). "In melanoma, BRAF mutations can result in enhanced MCL1 levels, thereby increasing resistance to apoptosis." (PMID 30197759, 2018). "We also compared the proposed methods against traditional IC50-based methods using 40 melanoma cell lines whose transcriptomes, proteomes, and, importantly, BRAF and related mutation profiles were available." (PMID 29435161, 2018). "Vemurafenib (B-RAF inhibitor) has been approved for the treatment of late stage and BRAF mutated melanoma as well as for the treatment of Erdheim-Chester Disease (a rare histiocytosis marked by recurrent BRAFV600E mutations in more than half of patients)." (PMID 30352565, 2018). "Overall, these data suggest that eNAMPT should be further studied as a disease marker for melanoma patients with a BRAF-mutated tumor." (PMID 29721178, 2018). "In a BRAF-mutated in vivo xenograft study, we treated A375 melanoma tumor-bearing animals with a BRAF mutated inhibitor (PLX4720), IT-139 or both in combination." (PMID 30038714, 2018). "In melanoma, BRAF mutations (mainly BRAF V600E) are found in 50% of melanoma BM, leading to a constitutive activation of the MAPK signaling pathway, promoting cellular growth, invasion, and metastasis." (PMID 29881714, 2018). "Discovery of frequent activating BRAF mutations in melanoma and treatment with selective inhibitors of this mutant kinase has led to dramatic responses in the setting of metastatic disease." (PMID 30188888, 2018). "One melanoma study focused on cancer resistant to inhibitors of BRAF, a commonly mutated protein in melanoma, and showed that a subset is sensitive to TBK1/IKKε inhibition (compound II, along with other inhibitors)." (PMID 30223576, 2018). "Melanoma patients harbouring a BRAF mutation often respond initially to BRAF inhibitor treatment, but typically resistance develops." (PMID 31763498, 2018). "We split the candidate features into four groups: (i) clinical variables (i.e., gender, age, pretreatment, and pathologic stage); (ii) mutation status of three well-known melanoma driver genes (BRAF, NRAS, and NF1); (iii) mutation load; and (iv) ECPAcell." (PMID 30297703, 2018). "Treatment with 6-thio-dG impaired the viability of NRAS-mutant melanoma cells, including cells driven by the secondary mutations in NRAS derived from melanoma patients with acquired resistance to BRAF and MEK inhibitors." (PMID 29695835, 2018). "Development of resistance to BRAF inhibitors in a mouse melanoma model was linked to restoration of the MDSC compartment." (PMID 30233579, 2018). "Metastatic melanoma carrying BRAF mutations represent a still unmet medical need as success of BRAF inhibitors is limited by development of resistance." (PMID 29721178, 2018).
melanoma (continued). "This treatment strategy offers a distinct advantage over MAPK inhibitors that can only be used for melanomas harboring the BRAF mutations, consequently limiting the population of patients that is eligible for their use." (PMID 30651927, 2018). "In cases with BRAF mutated melanoma, combining BRAF and MEK inhibitors further delays the development of resistance to about 11 months and patients with metastases at fewer than 3 organ sites and low LDH can even be stabilized for years." (PMID 29432466, 2018). "The identification of mutations of BRAF in human cancers is a milestone, opened new avenues in the therapy of melanoma and was a prerequisite for the development of small molecule BRAF inhibitors, most important vemurafenib and dabrafenib." (PMID 30053879, 2018). "The further loss of PTEN protein expression is significantly correlated with a decrease in overall survival (OS) and a reduction in the time it takes for brain metastases to arise in stage IIIB/C melanoma patients with BRAF (V600) mutations." (PMID 30053879, 2018). "BRAF is the most commonly mutated gene in melanoma; however, BRAF mutations have also been shown to be associated with NSCLC with a frequency of approximately 2–3% of cases." (PMID 29973561, 2018). "The present study shows that TEM combined with rMETase is effective for BRAF-V600E-negative melanoma PDOX similar to the BRAF-V600E-positive mutation melanoma." (PMID 29416666, 2018). "The aim was to examine if cellular immune markers in association with tumor proliferation rate and BRAF mutation status have an impact on prognosis in stage III melanoma." (PMID 28851300, 2017). "A phase I trial evaluating concurrent vemurafenib and ipilimumab treatment in patients with BRAF V600 mutation–positive melanoma demonstrated dose-limiting hepatotoxicity and was terminated." (PMID 29156850, 2017). "Targeting of the IGF1R pathway exerts potent anticancer effects and combined inhibition of MAPK, PI3K, and IGF1R successfully inhibited melanoma growth and overcame resistance of melanoma cells harboring BRAF and PTEN mutations." (PMID 28417283, 2017). "The clinical efficacy of selective BRAF inhibitors against BRAFV600E mutant melanoma patients inspired interest in CRC since somatic mutation of this gene occurs in ∼5–10% of colon cancer patients and is associated with poor prognosis." (PMID 27999210, 2017). "Current literature however, suggests a more aggressive nature of NRAS mutated melanomas compared to BRAF mutated or wildtype melanomas." (PMID 28522871, 2017). "The clinical availability of small molecule inhibitors specifically targeting mutated BRAF marked a significant breakthrough in melanoma therapy." (PMID 28415756, 2017). "BRAF-activating mutations have been reported in several tumours, but are particularly common in melanomas." (PMID 28651004, 2017). "Most melanoma patients (65%) bear a BRAF-mutated tumor and receive specific inhibitors targeting mutated BRAFV600E alone or in combination with MEK inhibitors, upstream of ERK." (PMID 28659921, 2017). "In this study, we assessed the presence of SDHD promoter mutations and SDHD protein expression in CM, OM and in melanoma cell lines, in which we already determined BRAF, NRAS, GNAQ and TERT promoter mutational status." (PMID 28662141, 2017). "Large-scale mutation analyses of malignant melanoma in the past identified mutations in the BRAF oncogene in 50% of melanoma samples." (PMID 27903987, 2017). "Aim of this study was to identify the best combination of methods for detecting BRAF mutations and investigate BRAF mutation heterogeneity within 100 primary melanomas and between primary melanoma and a subset of 25 matched metastatic samples." (PMID 28039443, 2017). "In approximately 50% of cutaneous melanomas BRAF mutations are found, while about 25% of melanomas harbor mutations in NRAS1." (PMID 28522871, 2017).
melanoma (continued). "Therapy for advanced melanoma has been improving with use of signal transduction inhibitors for tumors expressing BRAF mutations." (PMID 28134850, 2017). "The 98 melanoma samples were screened for BRAF V600E/K/R/D mutations by ARMS/Scorpion real-time PCR (BRAF RGQ PCR Kit, Qiagen, Germany)." (PMID 28881731, 2017). "We extended our analyses to A375 melanoma cells, which contain an activating V600E mutation in BRAF." (PMID 28982763, 2017). "Two human melanoma cell lines 2549 (wild type for BRAF, NRAS and cKIT) and 2338 (BRAF V600E mutated) were treated with 1 μM of each compound for 24 h, or DMSO as a control." (PMID 28878208, 2017). "Regarding melanoma, our findings establish that BRAF not only plays an obvious key role in BRAF-mutated tumours, but is also essential for NRAS-induced tumours." (PMID 28497782, 2017). "Several studies have now confirmed that the wild type BRAF allele is transcribed and processed correctly in mutant BRAF melanoma, and the shorter, variant BRAF transcripts are derived only from the mutant BRAF allele." (PMID 28503307, 2017). "Patients with stage IIIC BRAF V600E/K mutated melanoma who were free of disease after surgical resection received 4 months of adjuvant dabrafenib." (PMID 29285228, 2017). "In melanoma patients, this oral inhibitor of mutated BRAF protein only works in the presence of a BRAFV600E or V600 K mutation; melanoma cells without this mutation are not inhibited." (PMID 28915798, 2017). "This adds weight to the growing evidence base demonstrating that BRAF-positive melanoma patients are at increased risk of development of brain metastases." (PMID 28819707, 2017). "Our results demonstrate over-reliance on glycolysis can sensitize BRAF-mutated melanoma cells to targeted BRAF inhibitor treatment." (PMID 28205616, 2017). "Using a panel of 10 BRAF-mutated melanoma cell lines, we found most lines can variably utilize glucose and consume oxygen as part of mitochondrial respiration." (PMID 28205616, 2017). "Inhibitors of BRAF have been developed and recently approved to treat melanoma harboring activated V600E BRAF mutation that is identified in more than 50% of melanoma cases." (PMID 28265552, 2017). "Bosenberg has developed an especially useful model in which melanoma is driven by both BRAF mutation and PTEN loss." (PMID 28239469, 2017). "Approximately one third of the BRAF mutated melanomas in our cohort were found to have an associated nevus in the histologic examination." (PMID 28662062, 2017). "In this study, we inactivated LKB1expression by RNA interference in BRAF mutation and wild type melanoma cells respectively." (PMID 29371951, 2017). "The mutant allele frequency of BRAF V600E (M%BRAF) was recently shown to be highly heterogeneous in melanomas." (PMID 28668077, 2017). "Next, we analyzed the prognostic significance of EZH2 gain for overall survival (OS) and disease-free survival (DFS) in melanoma patients harbouring BRAF V600E mutation." (PMID 29202777, 2017). "Oral mucosal melanoma cells however show only infrequent mutations in either the NRAS or the BRAF molecular pathways that are common in melanoma of sun-exposed skin." (PMID 28638859, 2017). "Incidence of melanoma has been increasing in recent years, therapies for BRAF mutated melanoma currently exist however, a considerable part of melanoma can still not be treated despite intensive research." (PMID 28522871, 2017). "A joint NCI-SWOG randomised clinical trial evaluating the efficacy of intermittent compared with continuous dosing of dabrafenib and trametinib in patients with V600E mutated-BRAF positive melanoma is ongoing (ClinicalTrials.gov study NCT02196181)." (PMID 28717217, 2017). "Researches have noted that BRAF mutated melanomas tend to be of the superficial spreading type and often reveal peppering on dermoscopy." (PMID 28662062, 2017). "For example, melanomas with an activating BRAF mutation (V600E) respond well to inhibitors of this pathway at first." (PMID 28469568, 2017).